PRKCG (protein kinase C gamma)
Diseases named in the same sentence as PRKCG in open-access papers (continued):
Sharing a sentence is not in itself a finding about the gene and the disease.
glioblastoma (3 papers, 2021 to 2025). The most malignant astrocytic tumor (WHO grade IV). "PRKCG and WEE1, when upregulated, are known to be good prognostic markers in Glioblastoma, while high mRNA levels of RBL2 are known to be associated with HPV+ head and neck tumors." (PMID 34796107, 2021). "Though PRKCG’s role in glioblastoma remains unclear, its up-regulation following curcumin treatment in this study suggests a potential anti-tumorigenic effect, possibly influencing key dysregulated signaling pathways in cancer." (PMID 40430278, 2025).
hepatocellular carcinoma (3 papers, 2022 to 2024). A malignant tumor that arises from hepatocytes. "Missense SNPs in the PRKCG potentially affect its protein structure and function and thus may increase the likelihood or susceptibility of hepatocellular carcinoma development or progression." (PMID 36451234, 2022). "No studies have specifically established the relationship between PRKCG nsSNPs with structural and functional variations in PKC γ in the context of hepatocellular carcinoma (HCC)." (PMID 37344815, 2023).
Hypertension (3 papers, 2016 to 2021). The presence of chronic increased pressure in the systemic arterial system. "Similarly, the pathway-based 2-locus epistasis analysis indicated significant interactions between INSR and PRKCG for SBP and MAP; INS and PIK3R2 for DBP; PIK3CD and ATP1B2 for hypertension in the real data set." (PMID 27980660, 2016).
colorectal cancer (2 papers, 2017 to 2022). A primary or metastatic malignant neoplasm that affects the colon or rectum. "Because PRKCG expression in intestinal epithelium is much lower than that in neuronal tissues, the role of PKCγ in colorectal cancer progression is not well documented." (PMID 36404918, 2022).
episodic ataxia (2 papers, 2022). "Thus, it is tentative to speculate that PRKCG might be added to the genes responsible of episodic ataxia." (PMID 34292398, 2022).
non-small cell lung carcinoma (2 papers, 2015 to 2018). A group of at least three distinct histological types of lung cancer, including non-small cell squamous cell carcinoma, adenocarcinoma, and large cell carcinoma. "The genes included the pathway non-small cell lung cancer were E2F2, E2F3, TGFA, PRKCG, CDK6, EGF, and CDK4, which were all expressed at significantly higher levels in LUSC tissues in comparison to that in the non-cancer group." (PMID 29394946, 2018).
ovarian carcinoma (2 papers, 2023 to 2024). A malignant neoplasm originating from the surface ovarian epithelium. "The purpose of this study is to determine the predictive impact of PRKCG polymorphism in patients with ovarian cancer." (PMID 36672978, 2023). "The wet lab analysis of PRKCG SNP rs1331232028, like many other SNPs in multiple genes, including ERCC1, XPC, PIK3CA, ERBB2 and ERCC2, can be linked to ovarian cancer susceptibility." (PMID 36672978, 2023).
Parkinson disease (2 papers, 2018 to 2025). A progressive degenerative disorder of the central nervous system characterized by loss of dopamine producing neurons in the substantia nigra and the presence of Lewy bodies in the substantia nigra and locus coeruleus. "Early-onset Parkinson’s disease with atypical molecular imaging abnormalities in a patient carrying the de novo PRKCG mutation." (PMID 39968123, 2025).
renal carcinoma (2 papers, 2021). A carcinoma arising from the epithelium of the renal parenchyma or the renal pelvis. "Interestingly, the gene probes targeting FGF17, PRKCG, SSTR1, and SCTR predicted potential targeted agents for renal cancer metastasis and adjuvant immunotherapy, including 5224221, calmidazolium, and sulfasalazine." (PMID 35155566, 2021).
Cachexia (1 paper, 2020). Severe weight loss, wasting of muscle, loss of appetite, and general debility related to a chronic disease. "Four were common for local/cachexia (C1R, PRKCG, ELANE, SOST: all oppositely regulated) and four for metastatic/cachexia (SERPINA6, PDGFRA, PRSS2, PRSS1: all consistently changed), suggesting that stage and cachexia status might be molecularly separable." (PMID 33334063, 2020).
cognitive decline (1 paper, 2025). "Mutations in the protein kinase C gamma gene cause spinocerebellar ataxia 14 (SCA14), an autosomal dominant neurodegenerative disease leading to motor deficits and cognitive decline." (PMID 41288860, 2025).
gastric cancer (1 paper, 2022). A primary or metastatic malignant neoplasm involving the stomach. "The results of immunohistochemistry showed that the protein expression levels of RBP7, DES, SPP1, VIP, and PRKCG in gastric cancer tissues were higher than those in normal tissues, while PNOC, TNFRSF12A, and TUBB3 proteins are less expressed in gastric cancer tissues than normal tissues." (PMID 35174205, 2022).
heart arrhythmia (1 paper, 2019). "Five genes (PRKCG, EREG, BHLHE40, KLF10, and NAMPT) targeted by AA-miRNAs may contribute to the pathogenesis of heart arrhythmia such as AF." (PMID 31607954, 2019).
Huntington disease (1 paper, 2022). Huntington disease (HD) is a rare neurodegenerative disorder of the central nervous system characterized by unwanted choreatic movements, behavioral and psychiatric disturbances and dementia. "Only one was decreased in Huntington’s disease mice (PRKCG, Serine 373)." (PMID 36523271, 2022).
Hypercholesterolemia (1 paper, 2021). An increased concentration of cholesterol in the blood. "Examples of such master regulators are FOXO3, which controls mechanisms linked to MPN, RA, hypercholesterolemia, and hypertriglyceridemia, and PRKCG that controls canonical pathways related to regulation of blood pressure, platelet count, and function and linked to RA." (PMID 34580418, 2021).
Hyperglycemia (1 paper, 2024). An increased concentration of glucose in the blood. "Furthermore, we reveal that hyperglycemia-induced downregulation of tRF-Cys-GCA-029 promotes BC cell proliferation and glycolysis through interacting with PRKCG." (PMID 39039568, 2024).
ischemia (1 paper, 2025). A hypoperfusion of the BLOOD through an organ or tissue caused by a PATHOLOGIC CONSTRICTION or obstruction of its BLOOD VESSELS, or an absence of BLOOD CIRCULATION. "These prior works suggest that PRKCG functions deleteriously in response to ischemia initially, and later as a protective factor in the period of postischemic reperfusion." (PMID 40692577, 2025).
kidney cancer (1 paper, 2021). Primary or metastatic malignant neoplasm involving the kidney. "In addition, we performed qRT-PCR analysis on clinical specimens and found that the mRNA expression levels of FGF17, PRKCG, and SSTR1 were significantly different between kidney cancer tissues and normal tissues adjacent to the cancer." (PMID 35155566, 2021).
liver cancer (1 paper, 2023). An epithelial or non-epithelial malignant neoplasm that arises from the liver. "This is primarily the first study that has linked the decreased survival rates of liver cancer patients with the over expression of PRKCG through Kaplan Meier Analysis." (PMID 37344815, 2023). "The plot of the Kaplan–Meier estimator shows that as the expression of PRKCG increases (depicted by the red line in a series of declining horizontal steps), the survival rate of liver cancer patients decreases." (PMID 37344815, 2023).
mental disorder (1 paper, 2022). A disease that has its basis in the disruption of mental process. "Another intriguing finding is that PRKCG and LRRTM might be associated with mental disorders in TAO, providing a novel mechanistic explanation for clinical mental disorders occurring in TAO patients." (PMID 36056316, 2022).
multiple sclerosis (1 paper, 2020). A progressive autoimmune disorder affecting the central nervous system resulting in demyelination. "Individual contrast sensitivity results of PRKCG-patients are in the range of earlier studies in multiple sclerosis cohorts (with about half with a history of optic neuritis)." (PMID 32338350, 2020).
myocardial ischemia (1 paper, 2022). A disorder of cardiac function caused by insufficient blood flow to the muscle tissue of the heart. "Based on the results of network pharmacology analysis, first, the top four genes (PRKCA/MAPK3/PRKCG/PLA2G4A) and PRKCE (an isoform of the large PKC family) were picked up for validation in the animal model of surgery-induced myocardial ischemia." (PMID 35141226, 2022).
neuropathy (1 paper, 2024). A disorder affecting the nervous system that manifests with pain, tingling, numbness, and/or muscle weakness. "In this case, while the neuropathy findings of the patient were compatible with the variant in the SYNE1 gene, the variant in the PRKCG gene could not be ruled out and it is thought to be effective on the phenotype." (PMID 38587696, 2024).
pancreatic cancer (1 paper, 2025). "C1B5, a synthetic subdomain peptide of PRKCG, has shown anticancer potential in pancreatic cancer via the activation of T and NK cells in a study investigating the effect of cotreatment with C1B5 and gemcitabine in a pancreatic cancer mouse model." (PMID 40836964, 2025). "In the present study, a hypoxia- and immune-associated prognostic signature, which included 6 genes (GALR2, AGT, MAPT, PRKCG, CAMK2B, and PKP1), was established via LASSO Cox regression in patients with pancreatic cancer from the TCGA dataset and was further validated in 2 independent GEO datasets." (PMID 40836964, 2025).
Sepsis (1 paper, 2022). Sepsis is defined as life-threatening organ dysfunction caused by a dysregulated host response to infection. "This study predicted that the ceRNA network IL-17RA-1/miR-7847-3p/PRKCG might be the molecular mechanism underlying the processes of sepsis occurrence and development." (PMID 36274974, 2022). "Hence, IL-17RA-1 might regulate LPS-induced sepsis cell damage by mediating miR-7847-3p and mRNA PRKCG results and activating the MAPK signaling pathway." (PMID 36274974, 2022). "IL-17RA-1 could target miR-7847-3p, which mediates PRKCG expression via MAPK signaling pathway, to alleviate sepsis response." (PMID 36274974, 2022).
triple-negative breast carcinoma (1 paper, 2024). An invasive breast carcinoma which is negative for expression of estrogen receptor (ER), progesterone receptor (PR), and human epidermal growth factor receptor 2 (HER2). "In Triple-negative breast cancer (TNBC), aberrant expression of PRKCG was also noted." (PMID 39668814, 2024).
cancer (35 papers, 2014 to 2025). A tumor composed of atypical neoplastic, often pleomorphic cells that invade other tissues. "Whereas PRKCA, PRKCD, or PRKCG expression levels were negatively associated with the infiltration of immune cells in some cancers and positively correlated with immune infiltration in other cancers." (PMID 35174160, 2021). "Genetic variants of PRKCG or dysregulation of PKCγ have been implicated in human cancers." (PMID 39039568, 2024). "It shows that the over expression of PRKCG is hazardous for cancer patients and lowers their survival rates." (PMID 37344815, 2023). "Several SNPs in different PKC isoforms (rs454006, rs2242245, and rs8103851 of PRKCG, rs11079651 in PRKCA, and rs34367566 in PRKCB) have been reported to be linked with various types of cancer." (PMID 36672978, 2023). "Evidence also supports that glutamatergic signaling via NR2B activates neuronal PKCγ (protein kinase C gamma) as a mechanism to induce central sensitization in cancer bone pain." (PMID 36138983, 2022). "PRKCG (protein kinase C) can be activated by calcium and second messenger diacylglycerol, which promotes cell migration in cancer." (PMID 35646664, 2022). "For PRKCA, PRKCD, PRKCE, and PRKCG, the correlation between their expressions and HLAs enrichment scores were variable among different cancers." (PMID 35174160, 2021). "Otherwise, the correlations between PRKCA, PRKCD, PRKCE, and PRKCG expressions and the infiltration of the immune cells varied between cancer types." (PMID 35174160, 2021). "Our comprehensive gene expression analysis of all PKC isoforms revealed that three of the nine PKC coding genes (PRKCB, PRKCD and PRKCE) showed a down-regulation greater than two in the cancer tissue, while only one of the genes (PRKCG) was up-regulated." (PMID 26989024, 2016). "Pathway analysis revealed that PRKCG could be involved in focal adhesion molecules, tyrosine kinase inhibition, and cancer-related pathways, as well as choline metabolism in cancer." (PMID 40430278, 2025). "Based on PRKCG, the literature available on nsSNPs association with cancer is very limited and not studied in detail." (PMID 37344815, 2023). "The ability to identify genes with different splicing events between normal and tumor samples, as in the case of the PRKCG gene, may shed further light on the important role that SREs may play in cancer progression and open the door for further experimental validation." (PMID 26337677, 2015). "However, increasing evidence indicates that PRKCG may play essential roles in cancer and immunity." (PMID 40836964, 2025). "In summary, we found significant differences in the expression of FGF17, PRKCG, SSTR1, and SCTR in cancer, which are correlated with immune response and adjuvant therapy." (PMID 35155566, 2021). "Collectively, the expression levels of PRKCI and PRKCG were elevated in most of the significantly compared cancers, while PRKCA, PRKCB, PRKCE, and PRKCQ tended to be downregulated among most cancer types." (PMID 35174160, 2021). "In fact, PRKCG has analogous behavior to HER2 where exon 17 is included in 100 % of the transcripts in case of LUSC, KIRC, LIHC, PRAD, KICH cancer samples and skipped in the normal tissues." (PMID 26337677, 2015). "However, some cancers showed a lowered level of PRKCI (GBM, KICH, HIRC, THCA) and PRKCG (GBM, THCA)." (PMID 35174160, 2021). "DAG and IP3 signaling was not enriched with cancer drivers and did not have any low affinity CT drug targets, but did have six high affinity NP targets: PRKCG, E,A,D (Protein Kinase C), PDE1A (Phosphodiesterase 1A) and ADCY1 (Adenylate Cyclase 1)." (PMID 31214023, 2019). "Overall the top three enriched targets in the cluster can be classified into immunomodulation, which are PTPN2, protein kinase C beta type (PKC-β), protein kinase C eta type (PKC-η), and protein kinase C gamma type (PKC-γ), cancer, namely, TOPO1, and glucose homeostasis, such as SGLT2." (PMID 26989424, 2016).
cancer (continued). "As for GH1, PRKCG, and PSPN, they are not known prognostic biomarkers, but GH1 is still regarded as strongly related to cancer development because of its key role in the stimulation of growth factor secretion (i.e., IGF-1)." (PMID 36428747, 2022).
tumor (19 papers, 2014 to 2025). "Missense variants in exon 4 (C114Y/G123R/G123E) of the PRKCG gene have a relationship with tumor development and migration." (PMID 35860595, 2022). "The PRKCG gene encodes γPKC, which plays an important role in tumor genesis, proliferation, differentiation, and migration." (PMID 33968297, 2021). "PRKCG, a member of the serine/threonine kinase family, plays a pivotal role in cellular signaling pathways, contributing to tumor formation and progression." (PMID 38994113, 2024). "The pathological stages signify that as PRKCG expression has been upregulated, the tumor has become more aggressive and invasive." (PMID 37344815, 2023). "The protein kinase C gamma (PRKCG) gene is located on chromosome 19q13.42 and functions as the major receptor for tumor promoters." (PMID 35860595, 2022). "Protein kinase C gamma (PRKCG), as an isoenzyme of protein kinase Cs (PKCs), mediates IL-2 expression and tumor immune response." (PMID 35155566, 2021). "PRKCG is known to be a major receptor for phorbol esters, a class of tumor promoters." (PMID 26337677, 2015). "XHP intervention resulted in downregulation of these tumor suppressors (CCND2, PRKCG, CCN4) in tumor tissues and PC-3, DU145 cell lines, revealing XHP's regulatory role in the Wnt pathway." (PMID 38994113, 2024). "FGF17, PRKCG, and SSTR1 were detected with the same results in tumor tissues and adjacent normal kidney tissues, while SCTR was not significantly different." (PMID 35155566, 2021). "Subsequently, through OCLR scores, it was further confirmed that the expressions of FGF17, PRKCG, SSTR1, and SCTR were different in KIRC, which might lead to tumor metastasis by promoting tumor dedifferentiation." (PMID 35155566, 2021).
neurodegenerative disease (5 papers, 2019 to 2024). A disorder of the central nervous system characterized by gradual and progressive loss of neural tissue and neurologic function. "PRKCG and PSPN have a function in neurodegenerative diseases." (PMID 36428747, 2022).
neurological disorders (4 papers, 2013 to 2025). "PRKCG, one of the isozymes of protein kinase C (PKC), has been associated mainly with diseases of the nervous system in previous studies." (PMID 40836964, 2025).
infection (2 papers, 2013 to 2023). The state of being infected such as from the introduction of a foreign agent such as serum, vaccine, antigenic substance or organism. "A recent study involving proteomics of human tissue showed the effect of inflammation post-infection on the basal ganglia and the brain stem and suggested changes in trafficking in AMPA receptors via inflammation, along with increased abundance of protein kinases PRKCG, PRKCB, and CAMK2A/B." (PMID 38002279, 2023).
brain disorder (1 paper, 2023). A disease affecting the brain or part of the brain. "It has been shown that PRKCG is associated with brain disorders caused by hypoxia." (PMID 36803152, 2023).
movement disorder (1 paper, 2017). Neurological conditions resulting in abnormal voluntary or involuntary movement, which may impact the speed, fluency, quality and ease of movement. "Apart from such evidence, a specific mutation of PRKCG (SCA-14) has been reported to be associated with a typical movement disorder, which can be called Ramsay Hunt phenotype." (PMID 28255556, 2017).
PRKCG also shares sentences with these, for which no sentence is quoted: cerebellar ataxia (8 papers); Cognitive impairment (3); depression (3); acute myeloid leukaemia (2); Alzheimer disease (2); cerebellar degeneration (2); Friedreich ataxia (2); meningioma (2); Myoclonus (2); Pain (2); peripheral neuropathy (2); sarcoma (2); spinocerebellar ataxia type 1 (2); Tremor (2); age (1); anaplastic astrocytoma (1); ataxia telangiectasia (1); atherosclerosis (1); attention deficit-hyperactivity disorder (1); autoimmune thyroid disease (1); Autoimmunity (1); autosomal dominant disease (1); bone cancer (1); Burkitt lymphoma (1); cardiac hypertrophy (1); cataract (1); CNS tumors (1); dentatorubral-pallidoluysian atrophy (1); Diabetes (1); Diplopia (1).
A further 33 diseases each share a sentence with PRKCG in 1 paper.